ABCB1 (ATP binding cassette subfamily B member 1)
Diseases named in the same sentence as ABCB1 in open-access papers (continued):
Sharing a sentence is not in itself a finding about the gene and the disease.
tumor (continued). "We then developed a PDXO from a POBNCI_ACC004 resistant tumor and found that ABCB1 inhibitors re-sensitized the POBNCI_ACC004 resistant PDXO to both ADCT-701 and PBD, demonstrating the role of this drug efflux transporter in mediating acquired resistance to ADCT-701." (PMID 40595495, 2025). "The direct link we propose between DLK1, NOTCH1 signaling, and ABCB1 expression also suggests that ABCB1 inhibition could improve anti-tumor responses to DLK1-directed ADCs." (PMID 40595495, 2025). "ABCB1 upregulation may have played a role in taxol resistance at some point in the tumor’s evolutionary trajectory, but then additional drug resistance mechanisms became more dominant, such that inhibiting MDR1 in OCM is not sufficient to re-sensitize." (PMID 40466638, 2025). "This means that inhibitors that are a substrate for the ABCB1/ABCG2 transporters might also have reduced tumor cell distribution and efficacy for this reason." (PMID 40893689, 2025). "Besides, hypoxic tumor microenvironments stabilize HIF-1α/2α to upregulate drug efflux pumps (ABCB1/MRP1), while metabolic reprogramming through enhanced glutaminolysis and lipid metabolism supports redox homeostasis." (PMID 40771926, 2025). "MSI analysis revealed significant positive correlations for TACC3 and CXCL1 (p < 0.05), suggesting their potential roles in MSI-high tumor biology, whereas ABCB1, TGFBI, and VDR lacked significant associations with MSI status." (PMID 40791849, 2025). "This indicates that ABCB1 may serve as a prognostic marker in anthracycline-based chemotherapy regimens in these tumor types and target for the development of novel anthracycline derivatives." (PMID 40723843, 2025). "As the product of ABCB1 gene, P-gp is highly expressed in tumor cells." (PMID 40832604, 2025). "CDDP alone was less effective in inhibiting tumor growth in CAL 27/ABCB1 than in CAL 27 xenografts." (PMID 41189280, 2025). "We then developed a PDXO from a POBNCI_ACC004 resistant tumor and found that ABCB1 inhibitors re-sensitized the POBNCI_ACC004 resistant PDXO to PBD and ADCT-701 demonstrating the role of this drug efflux transporter in mediating acquired resistance to ADCT-701." (PMID 39416174, 2024). "Overexpression of P-glycoprotein (P-gp), a member of the ABC transporter family of ABCB1, is associated with the development of multidrug resistance (MDR), which is the most common cause of treatment failure in neoplastic diseases, including AML." (PMID 38542082, 2024). "It had been demonstrated that inhibition of MDR1/ABCB1 or MRP1/ABCC1 in the ABC transporter protein family could reverse doxorubicin resistance in tumor cells including osteosarcoma." (PMID 38420199, 2024). "Furthermore, the tumour tissues with histologically confirmed COS exhibited a significant downregulation in their mRNA expression profiles for ABCB1 (p-glycoprotein) and ABCC3 compared to the healthy donor muscles, as measured using real-time PCR." (PMID 39335211, 2024). "Moreover, in vivo studies using transplants of paclitaxel-resistant cells have demonstrated that silencing FTH1P3 leads to diminished ABCB1 protein levels and curtailed tumor growth, highlighting its direct influence on the miR-206/ABCB1 signaling pathway." (PMID 39286016, 2024). "ABCB1 is key mediator of zinc-mediated protection against to drug cytotoxicity in tumor cells." (PMID 39507258, 2024). "Among them, ABCB1/P-glycoprotein (P-gp) remains the best-studied and most potent ABC transporter to induce chemoresistance, and the upregulation of ABCB1/P-gp is closely linked with the emergence of MDR in tumor cells." (PMID 38611964, 2024). "To ascertain whether ABCB1 overexpression could be observed in in vivo settings, we analyzed tumor samples from the endpoints of multiple efficacy studies featuring AU-15330 detailed in our previous study." (PMID 38557192, 2024).
tumor (continued). "Specifically, EVs from drug-resistant tumor cells can horizontally transfer various components, such as drug-efflux pumps (e.g., ABCB1, ABCC1), miRNAs (e.g., miR-21-5p, miR-222), and regulatory proteins (e.g., TrpC5, EGFR), to drug-sensitive cells, thereby spreading a drug-resistant phenotype." (PMID 39403600, 2024). "However, overexpression of ABCB1 (also known as P-glycoprotein or multi-drug resistance protein 1) is another well-established mechanism of tumor resistance against TKIs." (PMID 38646295, 2024). "After paclitaxel enters human tumor cells, it is pumped out of the cells by ABCB1." (PMID 38674402, 2024). "The direct link we propose between DLK1, NOTCH1 signaling, and ABCB1 expression also suggest that ABCB1 inhibition could improve anti-tumor responses to DLK1-directed ADCs." (PMID 39416174, 2024). "Notably, transcriptional level of ABCB1 is also increased through leptin activation from tumor-related microenvironment." (PMID 37857015, 2023). "An essential ABC transporter in humans, P-glycoprotein (Pgp), which is encoded by the gene ABCB1, has been shown to play a crucial role in host detoxification of xenobiotic substances, leading to multidrug resistance in tumor cells." (PMID 37546821, 2023). "Thus, tumors of the intestine and ureters, and hepatocellular carcinoma, are characterized by a high constitutive expression of P-gp and (or) the ABCB1 gene." (PMID 35455394, 2022). "Moreover, since tumor cells themselves also often express ABCB1, they can therefore be resistant to EAI045." (PMID 36145346, 2022). "Human tumor transcriptomic data for 377 HCC patients also show a positive correlation of multiple ABC transporters including the ABCB1, ABCC3, ABCC9 and ABCG2 with GHR expression, while ABCC1,ABCC4 and ABCG1 levels correlated with IGF1R expression, confirming our in vivo observations." (PMID 35865483, 2022). "Indeed, prolonged exposure to taxanes upregulates the efflux transporter ABCB1 (P-glycoprotein) that pumps anticancer drugs out of tumor cells." (PMID 35908023, 2022). "ABCB1 overexpression is directly correlated with chemoresistance and tumor progression in PCa." (PMID 36135731, 2022). "Because lapatinib exerts anti-tumor effects on HER2-overexpressed CCA cells while simultaneously overcoming ABCB1–mediated chemoresistance, this proves that a lapatinib-gemcitabine combination-based therapy can be significantly more effective at treating HER2-positive CCA cases." (PMID 35463361, 2022). "ABCB1-mediated drug resistance appeared to be a dominant barrier for inhibition on KB-C2 tumor." (PMID 35459184, 2022). "Vandetanib also inhibits ABCB1, which could enhance the retention of coadministered cytotoxic agents in tumor cells." (PMID 35908023, 2022). "Based on this literature review, it can be assumed that whether MDR can be reversed by deglycosylation of ABCB1 depends on the choice of the (tumor) cell model." (PMID 36614114, 2022). "Generally, ABCB1 serves as a drug efflux pump actively reducing intracellular drug concentrations in resistant tumor cells, but its biological regulation remains unclear." (PMID 33834020, 2021). "Alterations over time in ABCB1 expression or intratumoral paclitaxel concentrations might also be a first sign of resistance of the tumor." (PMID 34858183, 2021). "Therefore, it is important to analyze the relationship between ABCB1 and prognosis for different tumor types separately." (PMID 33507672, 2021). "Moreover, metachronous lung metastases were reported to be more frequently ABCB1-positive compared with primary high-grade OS tumor samples, suggesting a gain of ABCB1 expression in secondary lesions." (PMID 34572110, 2021). "This could be due to different methodologies or thresholds for calling amplifications, the tumor fraction >7% cut-off selecting for patients more likely to have ABCB1 amplification, or our study population reflecting a more heavily pre-treated cohort." (PMID 34439209, 2021).
tumor (continued). "ABCB1 is an ATP-dependent drug efflux pump, which facilitates drug resistance in tumor cells." (PMID 34597626, 2021). "We also measured the expressions of ABCB1 mRNA and of P-gp protein in the tumor tissues." (PMID 34955854, 2021). "Silencing FOXC2-AS1 and ABCB1 reduces tumor growth during doxorubicin treatment." (PMID 34425750, 2021). "Overexpression of ABCB1 leads to the overexpression of membrane P-gp, with a consequent reduction in the concentration of intracellular paclitaxel, reducing the inhibitory effect of paclitaxel on tumor cells." (PMID 34955854, 2021). "However, MDR1 (ABCB1), the p-glycoprotein exporter, can lead to resistance by expelling Silvestrol out of the tumor cells." (PMID 35582375, 2021). "ABCB1 fusion-positive tumor tissues are usually accompanied by upregulation of ABCB1 expression, suggesting that gene fusion might allow ABCB1 to escape negative regulation and obtain a strong promoter." (PMID 34381020, 2021). "Tumor cells in MCJ KO MMTV mice expressed both isoforms of the mouse ABCB1 (ABCB1A and ABCB1B)." (PMID 33990571, 2021). "However, there are some challenges in developing ABCB1 inhibitors, such as the ubiquitous expression of ABCB1 (present in both normal and tumor tissues), complicated drug-drug interactions, and neurotoxicity." (PMID 32903706, 2020). "In contrast, [18F]AVT-011 showed lower uptake in mouse orthotopic tumors expressing clinically relevant levels of ABCB1 than in those with basal levels of ABCB1, and showed increased tumor uptake after ABCB1 inhibition, consistent with the behavior of an ABCB1 substrate." (PMID 31729540, 2020). "In contrast, in tumours and tissues where the ABCB1 promoter is silenced, translocation may be the only mechanism by which expression can be induced, favouring the selection of structural variants that replace the silenced promoter." (PMID 33167906, 2020). "Notably, the ABCB1 promoter has been found to be hypomethylated, hypermethylated or equally methylated in tumor tissues compared to normal breast tissues serving as controls." (PMID 33066132, 2020). "In this study, [18F]AVT-011 could discriminate between tumors expressing basal and high levels of ABCB1, as evidenced by the 32% reduced uptake in tumors with high levels of ABCB1 and by the 40% increase in tumor uptake following tariquidar administration." (PMID 31729540, 2020). "Indeed ABCB1 effluxes doxorubicin, which, together with cisplatin and methotrexate, is the first-line treatment in patients affected by this tumor." (PMID 32155954, 2020). "Another ABC transporter shown to regulate proliferation in tumor cells is ABCB1." (PMID 32587767, 2020). "In this study, we evaluate whether the BTK inhibitor, RN486, has similar effect as ibrutinib to enhance the tumor suppression activity of chemotherapeutic agents and overcome ABCB1-mediated MDR." (PMID 32984343, 2020). "ABCB1 was previously reported to contribute to DOC resistance in various tumor cells." (PMID 32581798, 2020). "Relative to tumor uptake at 45 min, tumor uptake (%ID/g) at 90 min increased by 27.5 ± 9.7% in the basal group, by 31.2 ± 13.3% in the intermediate group, and by 40.9 ± 3.7% in the high ABCB1–expressing group." (PMID 31729540, 2020). "Since the function of ABCB1 in mice was reported to be limited to specific tissues, it would be of interest to determine whether transgenic mice with high and broad expression of ABCB1 are less tumour prone, particularly in response to ABCB1 substrates." (PMID 31249297, 2019). "In this context, it has been suggested that ABCB1 inhibition may additionally improve access of anticancer drugs to tumor cells which overexpress ABCB1 in their cell membranes." (PMID 31832814, 2019). "In summary, numerous studies support the hypothesis that CD44 may contribute to tumor drug resistance by regulating ABCB1 expression." (PMID 31921125, 2019). "The xenograft tumor models in mice were established to evaluate the transfer of ABCB1 in vivo." (PMID 31830995, 2019).
tumor (continued). "In summary, we have shown that, ABCB1 expression in a sub-population of cells is correlated with poorer outcome and survival, presumably reflecting a sub-set of tumours that are both chemoresistant and locally invasive across the two clinical trial cohort assessed." (PMID 31311995, 2019). "Even in the presence of a disrupted BBTB with fenestrated capillaries, endothelial cells may have sufficient ABCB1/ABCG2 transport capacity to limit tumor distribution of such drugs." (PMID 31832814, 2019). "By inhibiting ABCC1 specifically, β-cholanic acid might augment accumulation of doxorubicin in ABCC1-expressing tumours, while retaining ABCB1’s ability to protect sensitive brain tissues to the damaging effects of doxorubicin." (PMID 29615646, 2018). "Patient, tumor, and treatment characteristics at inclusion in relation to ABCB1 C3435T genotype." (PMID 30370250, 2018). "Studies have shown that epigenetic modifications may regulate ABCB1/Pgp, as miRNAs are differentially expressed in tumor-resistant cells." (PMID 29316665, 2018). "There were no significant trends between the number of ABCB1 T-alleles and the patient-, tumor or treatment characteristics." (PMID 30370250, 2018). "ABCB1 expression level is often elevates in many tumor cells." (PMID 29285232, 2017). "Statistical analyses revealed that in tumor tissues the average promoter methylation status of ABCB1 (across the seven CpGs investigated) significantly correlated with the average promoter methylation status of ABCG2 (across the eight CpGs investigated) (r = 0.621; p = 0.010)." (PMID 27689338, 2016). "Two xenograft models confirm anti-tumor activity of simvastatin as well as ABCB1 downregulation." (PMID 26319048, 2016). "However, the number of included studies for the ABCB1 in recurrent tumor was limited (N = 3) that restricts the reliability of this result." (PMID 27812204, 2016). "For each of the seven CpGs in the ABCB1 promoter investigated, a statistically significant difference was found between tumor and tumor-adjacent tissue, tumor and tumor-distant tissue as well as between tumor and normal breast tissues of the control group." (PMID 27689338, 2016). "Twice daily dosing might produce an improved response, as could co-administration of an ABCB1 inhibitor that can achieve intra-tumor concentrations of lapatinib required to maximally inhibit HER2 and EGFR signaling." (PMID 26571496, 2015). "ABCB1 overexpression also reduced the anti-tumor activity of bosutinib in vivo." (PMID 26149173, 2015). "Interestingly, the patient dosed BID with the highest tumor concentration was also taking grape seed oil, which contains pentagalloylglucose, an ABCB1 inhibitor." (PMID 26571496, 2015). "The decrease of fluidity of tumor cell membrane resulted in the inhibition of ABCB1 function." (PMID 26506420, 2015). "ABCB1 expression was assessed in each of the tumours of origin by IHC." (PMID 24887326, 2014). "We hypothesise that the treatment of MB with current chemotherapeutic drugs, although effective as adjuvant therapy, leads to selection of an ABCB1 transporter expressing sub-populations of cells that in time can give rise to a more resistant tumour." (PMID 24887326, 2014). "However, the ABCB-1/P-gp expression of the 3-BrPA plus EPI group was significantly smaller than that of the EPI group in MCF-7/ADR tumor tissue." (PMID 25372840, 2014). "Thus, verapamil, cyclosporine A, and also propafenone analogs are inhibiting daunomycin efflux out of ABCB1 overexpressing tumour cells (i.e. act as inhibitors of ABCB1), but also act as substrates in polarized transport assays or ATPase activation assays." (PMID 23226167, 2012). "Moreover ABCB1 is induced by a wide variety of drugs, and is present on many tumours, rendering these cell types resistant to treatment with some cytotoxic drugs." (PMID 23133566, 2012).
tumor (continued). "The identification of cell-type specific controls on ABCB1 expression is important, because it indicates that it may be possible to maintain ABCB1 expression on brain endothelium, while reducing it on other cell types, for example in tumour therapy." (PMID 23133566, 2012). "These tumours showed concomitant nuclear β-catenin and high ABCB1 expression." (PMID 22460269, 2012). "The HIV-protease inhibitors (HIV-PIs) are substrates/inhibitors of the ABC transporters ABCB1, ABCG2, ABCC1, and ABCC2; induce and/or select for ABCB1 in human tumour cells; and sensitise cells to chemotherapeutics such as vincristine, vinblastine, and doxycycline in an HIV-PI-dependent manner." (PMID 21829205, 2011). "For example, PGP, encoded for by ABCB1 (also known as multidrug resistance gene 1), is affected by gene polymorphisms in tumour and non-malignant tissue." (PMID 21750553, 2011). "In this retrospective cohort study of patients with non-resectable PC, we examined whether tumor-tissue expression of drug efflux pumps ABCB1 and ABCG2 was associated with outcome of chemotherapy with gemcitabine and nab-paclitaxel." (PMID 40548120, 2025). "Drug-induced labile Zn2+ might also potentiate ABCB1-mediated drug export in tumor cells." (PMID 39507258, 2024). "Without zosuquidar treatment, the absence of ABCB1 lightly induced tumor growth, which may be associated with increased PD‐L1 expression when Abcb1a/b knocked out." (PMID 39229920, 2024). "The adenosine 5'‐triphosphate (ATP) binding cassette subfamily B member 1 (ABCB1) modulator zosuquidar disrupts PD‐L1 translocating from ER to Golgi apparatus, dramatically triggers autophagic degradation of PD‐L1, and exhibits significant anti‐tumor effect in vivo." (PMID 39229920, 2024). "These compounds could effectively reverse the ABCB1-mediated tumor MDR and show low cytotoxicity." (PMID 37233508, 2023). "Interestingly, ABCB1 is an HIF1A target gene, and HIF1A participates in the hypoxia-mediated multidrug resistance of tumor cells by inducing ABCB1 expression, reducing chemotherapeutic drug accumulation in tumor cells and inhibiting chemotherapy-induced apoptosis." (PMID 35659268, 2022). "Notably, the treatment line did not seem to affect PFS, suggesting that gemcitabine might be active even in some multi‐drug resistant tumors, possibly due to its activity in ABCB1‐expressing tumor cells." (PMID 35971325, 2022). "Overall, these results indicate that dFdCTP is potentially the substrate of ABCB1.Since dFdCTP is the most critical agent for gemcitabine-induced apoptosis, it may be the reason that the upregulation of ABCB1 induces the drug resistance of tumor cells." (PMID 35463361, 2022). "Most of the σ2 ligands not only show high affinity for the σ2 receptor but also exhibit excellent anti-tumor activity, and those with a 6,7-dimethoxy-1,2,3,4-tetrahydroisoquinoline structure could also interact with ABCB1." (PMID 36120340, 2022). "Since the intercellular transfer of ABCB1 occurs in different types of tumors, and in cells of different origin, it would have important implications to clarify whether ABCB1 transfer occurs in tumor patients and the relationship with chemotherapeutic response." (PMID 31830995, 2019). "Thus, inhibition of ABCB1 alongside chemotherapy may be of benefit to all patients, by increasing drug uptake as well as rendering previously therapy-resistant tumours sensitive to ABCB1 substrates." (PMID 31311995, 2019).